CCNB1 (cyclin B1)
Diseases named in the same sentence as CCNB1 in open-access papers (continued):
Sharing a sentence is not in itself a finding about the gene and the disease.
leukemia (15 papers, 2006 to 2022). A malignant (clonal) hematologic disorder, involving hematopoietic stem cells and characterized by the presence of primitive or atypical myeloid or lymphoid cells in the bone marrow and the blood. "One recent report from Vuletic and colleagues revealed that 13-cis-retinoic acid-treated HL-60 leukemia cells exhibited G0/G1 arrest and decreased cyclin B1." (PMID 23843871, 2013). "In primary tumour tissues and leukemia cell lines, accumulation of cyclin B1 is detected in the G1 phase." (PMID 20846384, 2010). "Constitutively active BTG2 in human leukemia U937 cells, induces G2/M cell cycle arrest by inhibiting the formation of the cyclin B1 and Cdc2 complex, thereby inhibiting the active kinase function of the complex." (PMID 16611356, 2006). "We utilized the data of gene expression profiling in samples with higher E2F1 expression and identified the genes associated with cell cycle progression (CCNA2, CCNE2, CCNB1, CCNB2 and, importantly, CCNE1) which were also found to be upregulated in leukemia cells exposed to DBF." (PMID 34564151, 2021). "Coronopilin increases cyclin B1 and p-Cdk1 (Tyr15) levels; however, the upregulation of γH2AX (p-H2AX Ser139) is involved in G1 phase arrest in leukemia (Jurkat and U937) cells." (PMID 35651747, 2022). "In MV-4-11 leukemia cells, co-incubation of reversine with CA4 and analogues concomitantly prevented mitotic arrest, as evidenced by cyclin B1 western blotting, and mitochondrial depolarisation, which suggested a causal connection." (PMID 28253265, 2017). "The observed effects of the combination on KMT2A-r leukemia cell survival were associated with downregulated expression of genes involved in proliferation and cell cycle progression including MKI67, CCNB1, CENPV, CDK4 and cMYC in infant KMT2A-r leukemia cells PER-485, PER-703 and PER-494." (PMID 35677155, 2022). "In THL-induced G2/M arrest of NB4 leukemia cells, the cyclin B1 was also decreased rather than increased." (PMID 19897545, 2011).
breast tumors (14 papers, 2006 to 2025). "The data presented identifies a role for miR-379 as a regulator of Cyclin B1 expression, with a significant loss of the miRNA observed in breast tumours." (PMID 23874748, 2013). "Through integrative analyses of transcriptomic datasets, we identified a germline-associated molecular signature, with CCNB1, CCNB2, PTTG1, RACGAP1, and UBE2C emerging as core EGT gene clusters markedly upregulated in breast tumors." (PMID 41009526, 2025). "The relative gene expression analysis of seven PGC-associated genes, including CCNB1, CCNB2, FEN1, MCM4, PTTG1, RACGAP1, and UBE2C, was conducted on the samples of breast tumors compared to healthy mammary tissues." (PMID 41009526, 2025). "Pharmacological inhibition of ACK1 using its inhibitor, (R)-9b dampened CCNB1, CCNB2 and CDC20 expression, caused G2/M arrest, culminating in regression of palbociclib-resistant breast tumor growth." (PMID 37330596, 2023). "Consistent with effect of CBX2/7 silencing on proliferation, CBX2/7 protein correlated significantly with proliferation markers CCNB1 and Ki67 in TCGA breast tumor tissues." (PMID 33400401, 2021). "Among the tumor specific CTLs, we found that CTLs specific for HLA-A2 restricted peptides derived from three well known shared breast tumor antigens, namely cyclin B1, MUC-1 and survivin." (PMID 17129372, 2006). "Among the primed CTLs, we demonstrate at least three specificities against the known shared breast tumor antigens cyclin B1, MUC-1, and survivin." (PMID 17129372, 2006). "For example, protein levels of CCNB1 (cyclin B1) were significantly higher (P = 7.28E‐13) in breast tumors with alterations in FAM83 family genes, whereas protein levels of GATA3 (P = 3.79E‐07), PGR (P = 5.77E‐07), and ESR1 (P = 9.20E‐07) were significantly lower." (PMID 28078827, 2017). "Cyclin B1 directly contributes to breast tumor cell proliferation and therapeutic resistance." (PMID 21172025, 2010). "The result of our experience has highlighted a significant overexpression of five CCNB1, CCNB2, PTTG1, RACGAP1, and UBE2C genes in breast tumors compared to the normal tissues (p-value < 0.05)." (PMID 41009526, 2025). "The average expressions of these genes in breast tumor samples compared to healthy mammary biopsies (tumor/healthy) were as follows: CCNB2 (0.483/−0.869), CCNB1 (0.262/−0.472), PTTG1 (0.398/−0.719), RACGAP1 (0.338/−0.609), and UBE2C (0.565/−1.016)." (PMID 41009526, 2025). "Regarding to the clinical relevance of our results, low expression levels of βArr1 were inversely correlated with CDC45, BUB1, CCNB1, and CCNB2 genes compared to normal tissue samples while positively correlated with poorer prognosis in breast tumours." (PMID 33452359, 2021). "TCGA data analysis also indicates the clinical relevance of our results, the low expression levels of βArr1 are inversely correlated with CDC45, BUB1, CCNB1, and CCNB2 genes compared to normal tissue samples while positively correlated with poorer prognosis in breast tumours." (PMID 33452359, 2021).
neuroblastoma (13 papers, 2011 to 2025). Neuroblastoma (NB) is the most common solid, extracranial childhood tumor. "In this study, it was demonstrated that O2/O3 treatment was able to reduce cell growth and to arrest cell cycle at G2 phase, by inhibiting the expression and localization of cyclin B1/cdk1 in neuroblastoma cell lines." (PMID 32992648, 2020). "As previously reported, upregulation of cdks is common in aggressive neuroblastoma, but only CCNB1/cdk1 were predictive of outcome both in the entire cohort as well as in the MYCN normal group when the Cyclin/cdk pairs were considered." (PMID 26029996, 2015). "Transient downregulation of CCNB1 or cdk1 was achieved by sequence-specific siRNAs in a panel of five neuroblastoma cell lines." (PMID 26029996, 2015). "To compare the ability of 4h and 4k to act as antimitotic agents in neuroblastoma cells, we assessed the levels of phosphorylated serine-10 on histone 3 (p-S10-H3) or CYCLIN B1 following 24 h incubation with 4h, 4k, or a matched dimethyl sulfoxide (DMSO) control." (PMID 40430358, 2025). "Importantly, STOX1A has been shown to directly regulate expression of mitotic cyclin CCNB1 in the SH‐SY5Y neuroblastoma cell line and participate in regulating the cell cycle." (PMID 37347215, 2023). "Thus, the CCNB1 and PKC genes in SK-N-MC cells can serve as potentialefficient targets for the agents targeted at neuroblastoma, includingsiRNAs." (PMID 22649691, 2011). "Furthermore, they identified that some special genes such as MAD2L, CCNB1 and BIRC5, which had a close relationship with ERCC6L were involved in the cell cycle pathway, thus ERCC6L may play an important role in neuroblastoma." (PMID 32891122, 2020). "Thus, MYCN is a sufficient but not necessary regulator of CCNB1/cdk1 expression, and upregulaton of CCNB1 and cdk1 is a common feature of neuroblastoma cell lines irrespective of their MYCN status." (PMID 26029996, 2015). "However, another study reported that STOX1A played a tumor-promoting role in human neuroblastoma cell SH-SY5Y and favored mitotic entry by binding directly to Cyclin B1 promoter, suggesting that STOX1 may promote or suppress malignancy depending on tumor cell types." (PMID 34722888, 2021). "However, the high expression levels of cdk1/CCNB1 in cell lines with normal MYCN, which are also found in primary tumors in the absence of MYCN amplification, left us to conclude that MYCN is a sufficient but not a necessary driver of cdk1/CCNB1 in neuroblastoma cells." (PMID 26029996, 2015).
endometrial cancer (12 papers, 2013 to 2024). Primary or metastatic malignant neoplasm involving the endometrium (mucous membrane that lines the endometrial cavity). "Cyclin B1 protein levels were previously reported to be associated with increasing grade and stage of type I endometrial cancer, as well as poorer cancer-specific survival by univariate analysis." (PMID 31906456, 2020). "Hui Cai and colleagues found that rs2069433 in CCNB1 was related to a reduction in endometrial cancer risk." (PMID 24386390, 2013). "As overexpression of cyclin B1 has been reported to contribute to development of aneuploidy, we also examined whether UCHL1 and cyclin B1 were associated with aneuploidy status in endometrial cancer." (PMID 31906456, 2020). "In endometrial cancer cell lines, sulforaphane induced phosphorylation of cdc2 on Tyr15, which is consistent with inhibition of the p21/cdc2/cyclin B1 complex driving G2/M progression." (PMID 32443471, 2020). "Four endometrial cancer cell lines that we tested showed a significant increase in the G2/M population when exposed to lithium and a concurrent elevation in cyclin B1 level." (PMID 23941783, 2013). "Our FACS analyses showed a G2/M arrest in endometrial cancer cells treated with GSK3β inhibitors, which prompted us to examine the expression of Cyclin B1, a cell cycle regulator that is rapidly up-regulated at G2 and degraded at mid-M-phase." (PMID 23941783, 2013). "The immunohistochemical analysis showed elevated CCNB1 protein levels in 12 cancer types in comparison to their normal tissue counterparts, specifically in bladder, breast, cervical, colon, liver, testicular, lung, ovarian, pancreatic, skin, stomach, and endometrial cancers." (PMID 38581717, 2024).
pituitary adenomas (10 papers, 2015 to 2024). "Previous studies have demonstrated that the CCNB1 gene is highly expressed in pituitary adenomas and is associated with invasiveness, suggesting that the CCNB1 gene plays an important role in the genesis and development of pituitary adenomas." (PMID 31585531, 2019). "Fittingly, CCNB1 has been shown to significantly affect the EMT characteristics of pituitary adenomas." (PMID 39518122, 2024). "Zhao reported that upregulation of CCNB1 played a part in the pathology of pituitary adenomas in the cell cycle." (PMID 33685467, 2021). "CCNB1 can also affect cavernous sinus invasion in pituitary adenomas through the epithelial-mesenchymal transition." (PMID 34675265, 2021). "A previous study by our team found that the CCNB1 gene is highly expressed in pituitary adenomas and correlates with invasiveness." (PMID 31585531, 2019). "The correlations between CCNB1 and E-cadherin expression and between CCNB1 and N-cadherin expression in pituitary adenomas were analysed." (PMID 31585531, 2019). "In the pathogenesis of pituitary adenomas, the regulation of G2/M phase transition and cyclin B1 caught particular attention." (PMID 31165412, 2019). "The specific mechanism by which CCNB1 affects the biological behaviour of pituitary adenoma invasion is unclear." (PMID 31585531, 2019). "CCNB1 and N-cadherin gene expression were significantly higher in the invasive pituitary adenomas than in the non-invasive pituitary adenomas." (PMID 31585531, 2019). "Twenty-four pituitary adenoma tissue samples were examined by RT-qPCR and Western blot to assess the mRNA expression levels and protein levels of CCNB1, E-cadherin and N-cadherin." (PMID 31585531, 2019). "The aim of this study was to investigate the relationship between CCNB1 expression levels in and cavernous sinus invasion by pituitary adenomas and to further elucidate the mechanism of cavernous sinus invasion by pituitary adenomas." (PMID 31585531, 2019). "The high expression of CCNB1 in pituitary adenoma affects cavernous sinus invasion by its involvement in EMT." (PMID 31585531, 2019). "After lentivirus-mediated knockdown of CCNB1 in rat pituitary adenoma cell lines (GH3 and GT1-1), cell function changes were studied." (PMID 31585531, 2019). "In our study, CCNB1 gene expression was significantly higher in invasive pituitary adenomas than in non-invasive pituitary adenomas." (PMID 31585531, 2019). "The RT-qPCR results showed that CCNB1 (p < 0.01) and N-cadherin (p < 0.01) were overexpressed in the invasive pituitary adenomas compared to the non-invasive pituitary adenomas and that E-cadherin (p < 0.001) expression was significantly decreased." (PMID 31585531, 2019). "The other genes including POU1F1, IGFBP3, and CCNB1 were also reported to correlate with pituitary adenomas." (PMID 25642247, 2015). "Procession of pituitary adenoma was enhanced by circRNA NFIX via CCNB1." (PMID 39135128, 2024). "By suppressing circNFIX or overexpressing miR‐34a‐5p, pituitary adenoma development was inhibited via targeting CCNB1, implying that the regulatory axis could be potential for treatment." (PMID 37953502, 2024). "In addition, they found that patients with invasive pituitary adenomas share higher CCNB1 expression than these with non-invasive pituitary adenomas." (PMID 33937049, 2021). "High CCNB1 expression in pituitary adenoma affects cavernous sinus invasion through EMT." (PMID 31585531, 2019). "Further clarification of the mechanism of CCNB1 actions in EMT may provide a new strategy for the treatment of pituitary adenomas." (PMID 31585531, 2019). "Similarly, CCNB1 was shown to be closely involved in the pathogenesis of pituitary adenomas in Zhang’s research." (PMID 31585531, 2019).
pituitary adenomas (continued). "The Western blot (WB) results also showed that CCNB1 (p < 0.001) and N-cadherin (p < 0.001) were overexpressed in the invasive pituitary adenomas compared to the non-invasive pituitary adenomas and that E-cadherin (p < 0.001) expression was significantly decreased." (PMID 31585531, 2019). "Furthermore, previous studies have suggested that CCNB1 may be closely related to pituitary adenomas that invade the cavernous sinus." (PMID 31585531, 2019). "CCNB1 gene expression was downregulated in the GH3 and GT1-1 pituitary adenoma cell lines; N-cadherin expression was also decreased, but E-cadherin expression was increased." (PMID 31585531, 2019). "Finally, our study revealed that the downregulation of CCNB1 impaired tumourigenesis and inhibited the EMT process in pituitary adenoma cells in vivo." (PMID 31585531, 2019). "Next, we examined whether CCNB1 regulates tumourigenesis and the EMT process in pituitary adenoma cells in vivo." (PMID 31585531, 2019). "The correlation between the CCNB1 gene and EMT may be a potential target for the diagnosis and treatment of pituitary adenomas." (PMID 31585531, 2019).
COVID-19 (9 papers, 2022 to 2025). A disease caused by infection with severe acute respiratory syndrome coronavirus 2. "The PPI network constructed in the present study using the identified DEGs revealed 5 hub proteins associated with MM, DLBCL, and COVID-19: CCNB1, HIST1H2BD, HIST1H1B, HIST1H2AC, and HIST1H3I." (PMID 36466549, 2022). "Therefore, Cyclin A2 may be another potential target for the treatment of COVID-19 and IS through the mechanism of affecting the level of cyclin B1/CDK1." (PMID 37184686, 2023). "Therefore, in this context, dysregulation of cyclin B1/CDK1 complex activity may be one of the mechanisms by which patients with COVID-19 are complicated with IS and affect the prognosis." (PMID 37184686, 2023). "Meanwhile, based on the currently available data on COVID-19 patients, CCNB1 may also be used as a potential biomarker of COVID-19 in peripheral blood mononuclear cells (PBMCs), thereby contributing to the development of drugs for the treatment of COVID-19 disease." (PMID 36466549, 2022). "The six biomarkers (CCNB1, CDK1, IRF4, LTA, MMP9 and OSM) can be served as the biomarkers for the treatment and prevention of COVID-19." (PMID 40300201, 2025). "The expressions of CCNB1, CDK1, IRF4, MMP9 and OSM were significantly higher in COVID-19 samples compared with matched controls, while LTA was down-regulated in GSE171110 training dataset." (PMID 40300201, 2025). "Consistent with the bioinformatic analysis, CCNB1, CDK1, IRF4, MMP9 and OSM were significantly overexpressed, while LTA was de-expressed in COVID-19 patients compared with healthy controls." (PMID 40300201, 2025). "A previous observational study has suggested that CCNB1 and CDK1 is the hub regulatory genes in the pathogenesis of COVID-19 and highly expressed in COVID-19." (PMID 40300201, 2025). "The abnormal expression of CCNB1 and CDK1 indicated that the cell cycle and proliferation was dysregulated in COVID-19." (PMID 40300201, 2025). "Geldanamycin has also been observed to downregulate the expression of the cell cycle genes CCNB1 and UBE2C in COVID-19, which can potentially serve as effective antiviral and anti-inflammatory agents." (PMID 38932215, 2024). "We screened for statistically significant hub genes and found that ACTB was in low expression of both BD and COVID-19, and ASPM, CCNA2, CCNB1, and CENPE were in low expression of BD and high expression of COVID-19." (PMID 37335738, 2023). "The network pharmacology analysis identified seven core targets (namely, AURKA, CDK1, CCNB1, CCNB2, CCNE1, CCNE2, and TTK) of curcumol in patients with COVID-19 and LUAD." (PMID 35520289, 2022). "We identified seven core pharmacological targets of curcumol, namely, AURKA, CDK1, CCNB1, CCNB2, CCNE1, CCNE2, and TTK, in treating LUAD and COVID-19." (PMID 35520289, 2022). "The molecular network analysis using Cytoscape highlighted seven core targets of curcumol, namely, AURKA, CDK1, CCNB1, CCNB2, CCNE1, CCNE2, and TTK in COVID-19 and LUAD." (PMID 35520289, 2022).
head and neck squamous cell carcinoma (9 papers, 2008 to 2025). A squamous cell carcinoma that arises from any of the following anatomic sites: lip and oral cavity, nasal cavity, paranasal sinuses, pharynx, larynx, and salivary glands. "CTD analysis showed that KNTC1, MCM2, CKAP2, RACGAP1, CCNB1 were associated with head and neck squamous cell carcinoma, necrosis, inflammation and hepatomegaly." (PMID 37480569, 2023). "Five genes (KNTC1, MCM2, CKAP2, RACGAP1, CCNB1) were found to be associated with head and neck squamous cell carcinoma, necrosis, inflammation and hepatomegaly." (PMID 37480569, 2023). "Whereas, up-regulation of lincRNA-p21 resulted in G1 arrest in HN6 and Cal27 cells as well as reducing the expression levels of several cell cycle regulating factors such as Cyclin B1 and Cyclin D1 along with the apoptosis induction in head and neck squamous cell carcinoma (HNSCC) cells." (PMID 32582435, 2020). "However, in head-and-neck squamous cell carcinoma, PLK1 siRNA significantly increased the CCNB1 mRNA level." (PMID 29246203, 2017).